CRP (C-reactive protein)
Diseases named in the same sentence as CRP in open-access papers (continued):
Sharing a sentence is not in itself a finding about the gene and the disease.
astrocytomas (1 paper, 2017). "Previous research has shown that elevated levels of CRP preoperatively in patients with high grade astrocytoma is correlated to decreased survival." (PMID 28880870, 2017). "The role of CRP in high grade astrocytomas would be interesting to explore further in future research." (PMID 28880870, 2017).
autoimmune inner ear disease (1 paper, 2023). A syndrome characterized by rapidly progressive sensorineural hearing loss (SNHL), that is often bilateral, and is potentially reversible. "Data on Meniere’s disease and CRP are limited; a study found that CRP tends to be elevated in autoimmune inner ear disease patients, but another study reported that more than half of these cases had an elevated CRP, and studies on Cogan’s syndrome and CRP are sparse." (PMID 37873776, 2023).
B-cell lymphoblastic leukemia (1 paper, 2024). "In studies, patients with B-cell lymphoblastic leukemia following CAR-T cell therapy presented elevated levels of IL-1α, IL-2, IL-3, IL-5, IL-6, IL-8 IL-10, IL-15, IFN- γ, procalcitonin, CRP, G-CSF, GM-CSF, and MCP-1, and their levels were linked to the severity of neurotoxicity." (PMID 39409959, 2024).
benign breast tumors (1 paper, 2023). "The WBC, NEU, and CRP values in patients with GLM were significantly higher than those in patients with benign breast tumors (P < 0.01)." (PMID 37817809, 2023). "The WBC, NEU, and CRP values were significantly higher in patients with GLM than in those with benign breast tumors (P < 0.01)." (PMID 37817809, 2023). "IL-6, NEU, NEU%, and CRP values were significantly elevated in patients with GLM compared to those with benign breast tumors, indicating that IL-6 plays an important role in the development and onset of GLM." (PMID 37817809, 2023). "This study aimed to explore the differences and significance of peripheral blood IL-6 and related cytokines, routine blood test results, and C-reactive protein (CRP) levels between patients with GLM and benign breast tumors." (PMID 37817809, 2023). "Comparison of routine blood test results and CRP levels between patients with GLM and benign breast tumors (X ̄±s)." (PMID 37817809, 2023).
beta thalassemia (1 paper, 2010). Beta-thalassemia (BT) is characterized by deficiency (Beta+) or absence (Beta0) of synthesis of the beta globin chains of hemoglobin (Hb). "In one study, baseline elevations in CRP in adult HbSS/Sβ0Thalassemia patients were correlated with a ‘sickle severity index’ as compared to heterozygous sickle beta thalassemia patients." (PMID 19995398, 2010).
beta-thalassemia intermedia (1 paper, 2023). Beta-thalassemia (BT) intermedia is a form of BT characterized by mild to moderate anemia which does not or only occasionally requires transfusion. "Previous studies have found that the level of inflammatory cytokines such as C-reactive protein (CRP) increases in patients with beta thalassemia intermedia." (PMID 35347380, 2023).
bile duct tumor (1 paper, 2020). "In the current study, CRP/Alb ratio >0.089 was significantly associated with a large tumor size and bile duct tumor invasion and tended to be associated with vascular invasion in patients with ICC." (PMID 32856868, 2020). "Compared with the CRP/Alb ratio ≤0.089 group, the CRP/Alb ratio >0.089 group comprised significantly more patients with tumor size >5 cm (50% vs. 21.4%, p = 0.019) and bile duct tumor invasion (65.4% vs. 39.3%, p = 0.034)." (PMID 32856868, 2020).
Blindness (1 paper, 2025). Blindness is the condition of lacking visual perception defined as a profound reduction in visual perception. "However, the emergence of systemic symptoms, including transient monocular blindness, scalp tenderness, jaw claudication, weight loss, and fatigue, alongside abnormal laboratory results (ESR of 85 mm/hr and CRP of 50 mg/L), prompted further evaluation." (PMID 40125098, 2025).
blood circulation disorder (1 paper, 2022). "CRP could increase vascular endothelial factor, leading to the thickening of the basilar membrane of small vessels, and blood circulation disorder." (PMID 35443645, 2022).
blood disease (1 paper, 2022). A disease that occurs in the blood. "Recently, much work has been done to explore the association of inflammation, as reflected by C reactive protein (CRP), interleukin-6 (IL-6), and IL-8, with VCZ concentration in transplantation patients, patients with blood diseases, and critically ill patients." (PMID 35462904, 2022).
blood pressure (1 paper, 2022). "The higher albuminuria found in adult control and treated animals is compatible with the long-term effect of high blood pressure, as well as the pro-hypertensive effect of CRP transgene in these animals." (PMID 36140169, 2022).
bone marrow disorder (1 paper, 2025). Any disease of the bone marrow. "Certain strains, such as Lactobacillus and Bifidobacterium, have been shown to lower levels of inflammatory markers such as C-reactive protein (CRP) and interleukin-6 (IL-6), which are typically increased in bone marrow disorders." (PMID 40292219, 2025).
bone marrow failure (1 paper, 2022). "In contrast, our present p15 endocan fragment results suggest that the serum levels of p14 endocan fragment remain low during the whole period of severe bone marrow failure, even during febrile neutropenia with increased CRP levels." (PMID 35454082, 2022).
bone metabolism disorders (1 paper, 2024). "Proinflammatory cytokines, including TNFα, IL6, IL18, IL17, and CRP appear to activate osteoclasts and osteoblasts, leading to bone metabolism disorders." (PMID 38272859, 2024).
brain abnormalities (1 paper, 2013). "Systemic inflammation was assessed with a composite measure of commonly used circulating inflammatory markers (C-reactive protein, CRP, and tumor necrosis factor-alpha, TNFα) that have been linked to brain abnormalities in community-based samples of older persons." (PMID 23991174, 2013).
bulimia nervosa (1 paper, 2020). A disorder characterized by recurrent episodes of binge-eating over which the individual feels a lack of control; these episodes of binge-eating are followed by recurrent compensatory behavior to prevent weight gain, usually self-induced vomiting. "We also found similar associations between higher levels of CRP and lower odds of binge eating, purging, and bulimia nervosa (although for the latter two evidence of an association was weak and absent, respectively)." (PMID 32755646, 2020).
campylobacter enteritis (1 paper, 2023). "Except for campylobacter enteritis, in which CRP can be notably raised, old data suggest that CRP > 12 mg/L could be a useful tool for predicting children bacterial gastroenteritis, but a more recent study found that CRP > 95 mg/L during the first 48 h is suggestive of bacterial gastroenteritis." (PMID 37873776, 2023).
cancers of the hypopharynx (1 paper, 2022). "To date, no Chinese studies have investigated the effects of serum CRP level on the prognosis of patients with HNSCC, including cancers of the hypopharynx, nasopharynx, larynx, and oropharynx." (PMID 35847918, 2022).
carcinoid tumor (1 paper, 2020). A slow growing neuroendocrine tumor, composed of uniform, round, or polygonal cells having monotonous, centrally located nuclei and small nucleoli, infrequent mitoses, and no necrosis. "Preoperative CRP levels were lower in female patients and the proportion of carcinoid tumors differed among male and female patients." (PMID 33080990, 2020).
carcinoma in situ (1 paper, 2009). "CRP was found in NAF samples, and it was not significantly related to serum CRP levels, suggesting that CRP presence in NAF may reflect the early development of proliferative changes in the ductal epithelium preceding carcinoma in situ and invasive carcinoma." (PMID 22276018, 2009).
cardiac conduction disorders (1 paper, 2023). "Another study revealed that CRP assumes a proarrhythmic role by directly influencing calcium homeostasis in cases of cardiac conduction disorders." (PMID 37777746, 2023).
cardiac sarcoidosis (1 paper, 2021). Sarcoidosis affecting the tissues of the heart. "We identified 30 subjects with cardiac sarcoidosis who had CRP 3–20 mg/L (we excluded patients with CRP > 20 mg/L as they may have had a concomitant bacterial infection, and therefore might be excluded upon screening)." (PMID 34749739, 2021).
carpal tunnel syndrome (1 paper, 2024). Entrapment of the median nerve in the wrist that is characterized by numbness, tingling and painful movement. "C-reactive protein serum levels are higher in patients with carpal tunnel syndrome and proximal symptom spread." (PMID 38606315, 2024).
Central hypothyroidism (1 paper, 2021). A type of hypothyroidism due to an insufficient stimulation of an otherwise normal thyroid gland. "Our results showed that the patients with central hypothyroidism had higher WBC count, neutrophil count, CRP and procalcitonin levels, suggesting a pronounced systemic inflammation in central hypothyroidism." (PMID 34781943, 2021).
cervical spondylosis (1 paper, 2026). "Laboratory markers, such as CRP and white blood cell count, improved over time, and cervical spine X-rays revealed cervical spondylosis with C4-C5 protrusion, explaining her symptoms." (PMID 42078271, 2026).
Chagas cardiomyopathy (1 paper, 2021). A disease of the cardiac muscle developed subsequent to the initial protozoan infection by trypanosoma cruzi. "Others noted elevated serum levels of IL-6 and C-reactive protein (CRP) in Chagas cardiomyopathy patients." (PMID 34479416, 2021).
channelopathy (1 paper, 2015). Channelopathies are a group of diseases caused by the dysfunction of ion channel subunits or their interacting proteins. "Importantly, the effect of mutated channelopathy and pumps on CRP levels persisted after adjustments for level of PAC and potassium level." (PMID 26066391, 2015). "The mechanism of high CRP in non-mutation carriers and its impact on channelopathy is still not clear; therefore, the hypothesis that oxidative stress is a causative factor for the generation of autonomous aldosterone production still needs further study." (PMID 26066391, 2015).
chronic allograft nephropathy (1 paper, 2023). "High CRP serum concentrations also represent a negative predictive value in renal allograft recipients, being also involved in anticipation of chronic allograft nephropathy and graft failure." (PMID 36826577, 2023).
chronic asthma (1 paper, 2017). An asthma that is characterized by the development of persistent airway inflammation and recurrent attacks of breathlessness and wheezing, which vary in severity and frequency. "An increase in eosinophils in relation with shorter LTL, as well as with altered values of CRP, is in line with a study conducted on asthmatic subjects, in which chronic asthma (life-course-persistent asthma), via systemic eosinophilic inflammation, associated with LTL." (PMID 28536575, 2017).
chronic gingivitis (1 paper, 2023). Chronic painless inflammation of the gums. "As such, patients with chronic gingivitis have higher serum concentrations of inflammatory markers such as C-reactive protein." (PMID 37046667, 2023).
chronic meningitis (1 paper, 2004). Chronic form of meningitis (disease). "Although there was a persistent mild neutrophilia, both the CRP and ESR were normal throughout the course of the disease, which, whilst being highly unusual for acute meningitis, has been reported, in chronic meningitis." (PMID 15469610, 2004).
Cluster headache (1 paper, 2025). A type of headache characterized by repeated attacks of unilateral pain lasting 15 to 180 minutes and associated with local autonomic signs. "IL-6 facilitates the acute phase response (raising CRP) and can modulate pain pathways; in fact, an IL-6 blocker (tocilizumab) has shown some benefit in cluster headache, hinting at a role in cranial pain disorders." (PMID 41377228, 2025).
CMV retinitis (1 paper, 2019). "Only one of the HIV-positive patients exhibited normal values of both ESR and CRP; this patient was diagnosed with CMV retinitis." (PMID 30411142, 2019).
colorectal adenocarcinoma (1 paper, 2024). The most common type of colorectal carcinoma. "The tumor marker carcinoembryonic antigen (CEA) was generally increased, as were alkaline phosphatase (ALP), creatinine, and C-reactive protein (CRP), in patients with colorectal adenocarcinoma." (PMID 39337548, 2024).
constrictive pericarditis (1 paper, 2022). A heart disorder in which the pericardial sac becomes thickened and fibrotic, tightening the myocardium and impeding the normal myocardial function. "However, we have considered clinical biological (CRP) and Echocardiographic features as sufficient to make the diagnosis of constrictive pericarditis in our technologically under-equipped medical centers." (PMID 35945602, 2022).
convulsion (1 paper, 2024). A rapid and repeated body muscle contract that results in an uncontrolled shaking of the body. "In concordance with the result of previous studies, we found that convulsions, PCT, urea, γ-GT, AST, A/G, α-HBD, ALT, ALP, and CRP were important predictors of ANE." (PMID 38769496, 2024).
COPA syndrome (1 paper, 2025). "Furthermore, exome sequencing confirmed the presence of COPA syndrome despite the absence of typical markers like RF and ANA profile, and normal CRP and ESR." (PMID 41158762, 2025).
coronary restenosis (1 paper, 2025). Recurrent narrowing or constriction of a coronary artery following surgical procedures performed to alleviate a prior obstruction. "Our pooled analysis which included 19 studies, and performed using random effects, demonstrated a significant association between higher baseline CRP levels and the incidence of angiographically confirmed coronary restenosis (SMD = 0.41; 95% CI = 0.16, 0.66; p = 0.001." (PMID 40309624, 2025).
cortical atrophy (1 paper, 2025). "Combined cytokines and chemokines, including CRP and IL-6, have been linked to severe cortical atrophy due to enhanced Aβ influx, reduced clearance across the BBB, and increased neural production of Aβ." (PMID 41294487, 2025).
Degos disease (1 paper, 2021). "Elevated ESR or CRP is associated with MAP and may be a predictor of systemic involvement for patients with Degos disease." (PMID 33957947, 2021).
demyelinating disease (1 paper, 2023). A broad group of disorders that affect the myelin sheaths that cover the neurons. "CRP was significantly higher in CNSL than in demyelinating diseases (p = 0.0147), and showed a higher tendency in CNSL than in infectious diseases (p = 0.0642)." (PMID 37501501, 2023).
denture stomatitis (1 paper, 2014). Inflammation of the mouth due to denture irritation. "Importantly, patients having clinical signs of oral candidosis or denture stomatitis also showed elevated levels of CRP, and authors suggested that it may be the explanation of the elevated CRP levels seen in the edentulous." (PMID 25045683, 2014).
diabetic eye disease (1 paper, 2024). A group of disorders affecting the eye in patients with diabetes mellitus. "In the higher Lp(a) group, there were significantly elevated levels of diabetic eye disease, apoB, hs-CRP, TC, LDL-C, sdLDL-C, and HCY, compared to the lower Lp(a) group (p < 0.05)." (PMID 39296136, 2024).
diseases of the genitourinary system (1 paper, 2021). "Respiratory diseases had 81.2% of patients with elevated CRP, followed by neoplasms (71.4%), infectious (66.6%), and cardiovascular and digestive diseases (both with 60.0%), diseases of the genitourinary system (65.0%), and diseases of the nervous system (57.1%)." (PMID 34830693, 2021).
Dry skin (1 paper, 2025). Skin characterized by the lack of natural or normal moisture. "The primary risk factors included age, duration of dialysis, primary disease, dry skin, serum calcium (Ca), serum phosphorus (P), calcium-phosphorus product, C-reactive protein, intact parathyroid hormone (iPTH), β2-microglobulin (β2-MG), blood urea nitrogen (BUN), and serum creatinine (SCr)." (PMID 40442691, 2025).
Dyskinesia (1 paper, 2024). A movement disorder which consists of effects including diminished voluntary movements and the presence of involuntary movements. "The aim of this study was to compare the levels of certain analytes, including IL-6, TNF-α, CRP, visfatin, progranulin, and 25(OH)-vitamin D, across three distinct groups, namely PD patients without dyskinesia, PD patients with dyskinesia, and healthy controls." (PMID 38392998, 2024).
dysthymic disorder (1 paper, 2022). A chronic mood disorder in which the symptoms are similar to, though milder than, those diagnosed in depression. "Moreover, in men the more recent dysthymic disorder or at least moderate depressive episode was associated with higher CRP levels, compared to females (p = 0.006)." (PMID 35163538, 2022).
Dystonia (1 paper, 2021). An abnormally increased muscular tone that causes fixed abnormal postures. "We observed elevated levels of inflammatory markers, reflected by increased CRP levels in response to electrical stimulation applied to the brain and spinal cord of patients with PD, dystonia, and chronic pain." (PMID 33503960, 2021).
Eisenmenger syndrome (1 paper, 2022). "Reversal of flow through a septal defect in Eisenmenger syndrome is associated with a systemic proinflammatory response, with increased C-reactive protein (CRP) and Interferon (IFN)-γ levels." (PMID 35694664, 2022).
emphysematous cholecystitis (1 paper, 2025). Cholecystitis resulting from infection by gas producing organisms. "A prospective cohort study of 556 subjects also found that CRP is the best inflammatory marker for predictive of advanced AC (gangrenous cholecystitis, pericholecystic abscess, hepatic abscess, biliary peritonitis, emphysematous cholecystitis) and of conversion to open surgery." (PMID 40989157, 2025).
encephalitozoonosis (1 paper, 2024). Infection with fungi of the genus encephalitozoon. "The other two techniques mentioned before, Western blot analysis and CRP measurement, have a rather less frequent use due to labor-intensive features and non-specificity to encephalitozoonosis, respectively." (PMID 39770381, 2024).
endometrial polyp (1 paper, 2024). A benign nodular lesion protruding above the surface of the endometrium. "In the present study, we demonstrated that hysteroscopic polypectomy in women with suspected endometrial polyp by 2D ultrasound and with a history of prior failed IVF attempt, resulted in a statistically significant improvement in the number of CRP (65%) and total number of pregnancies (72.5%)." (PMID 39200896, 2024).
endomyometritis (1 paper, 2019). An inflammation of the endometrium and the myometrium. "Therefore, the question remains which of these factors cause a significant increase in CRP and what role CRP plays as an inflammatory/infection parameter in the immediate postpartum to discriminate between physiologic changes and pathologic processes such as endomyometritis?" (PMID 32082531, 2019).
Enterococcus faecalis infection (1 paper, 2024). A bacterial infection induced by Enterococcus faecalis which is the most prevalent species (along with Enterococcus faecium) cultured from humans, accounting for more than 90% of clinical isolates. "The mean maternal age was 35 and 29.3 years in the cerclage and non-cerclage groups, respectively, CRP and WBC were significantly higher in the cerclage group, and Enterococcus faecalis infection was observed in the cerclage group but not in the non-cerclage group." (PMID 38671355, 2024).